PDE8B (phosphodiesterase 8B)
Diseases named in the same sentence as PDE8B in open-access papers (continued):
Sharing a sentence is not in itself a finding about the gene and the disease.
Leydig cell tumor (1 paper, 2022). A sex cord-stromal tumor occurring in the testis and rarely in the ovary. "Interestingly, we found that the expression of PDE8B but not of PDE8A is increased in transformed Leydig cells (Leydig cell tumors-LCTs) compared to non-tumoral cells." (PMID 36277728, 2022).
McCune-Albright syndrome (1 paper, 2018). McCune-Albright syndrome (MAS) is classically defined by the clinical triad of fibrous dysplasia of bone (FD), cafe-au-lait skin spots, and precocious puberty (PP). "In addition to postzygotic somatic mosaicism of GNAS in McCune-Albright syndrome, rare examples of hereditary PBMAH have been described in the setting of APC-, MEN1-, FH-, PDE8B-, and PDE11A variant-driven pathogenesis." (PMID 29594118, 2018).
myopia (1 paper, 2024). "Drawing upon Zhao’s research, it was observed that reductions in PDE4B and PDE8B levels—enzymes responsible for the catabolic breakdown of cyclic AMP (cAMP)—are associated with the progression of myopia, presumably through the elevation of scleral cAMP concentrations." (PMID 38605967, 2024).
primary immunodeficiency (1 paper, 2023). "There was a correlation between PDE8B and DNA replication, hematopoietic cell lineage, intestinal immune network for IgA production, primary immunodeficiency, and ubiquitin-mediated proteolysis." (PMID 37179305, 2023).
tumor (6 papers, 2012 to 2024). "This suggests that PDE8B may perform divergent, possibly even contradictory roles depending on the specific type of tumor cell, akin to recent findings that miRNAs, although highly expressed, can suppress tumor growth." (PMID 38989284, 2024). "Tissue studies indicated that PDE8B expression decreases significantly in higher-grade GBM tissues compared to adjacent normal tissues, paralleling the progression to an immunosuppressed tumor microenvironment where both immune cells and PDE8B expression are diminished." (PMID 38989284, 2024). "In tumor tissues, the methylation frequencies of DBC1, PDE8B, and ZNF582 were 13/14 (93%), 4/14 (29%), and 14/14 (100%), respectively." (PMID 22815913, 2012).
cancer (5 papers, 2012 to 2024). A tumor composed of atypical neoplastic, often pleomorphic cells that invade other tissues. "Activators of PDE8 and PDE11 would have potential value in the treatment of tumors with hemizygous loss or inactivation of PDE8B of PDE11A, respectively, and potentially in other cAMP-pathway cancers characterized by elevated levels of cAMP." (PMID 36313756, 2022). "DBC1, ZNF582, and PDE8B demonstrated high methylation levels in more than four cancer pools, and were chosen for further validation in individual samples." (PMID 22815913, 2012).
neurological diseases (2 papers, 2025 to 2026). "Dysregulation of PDE8B is associated with the onset of various diseases, including cardiovascular diseases, neurological disorders, and metabolic diseases." (PMID 40894479, 2025). "PheWAS results showed that FAM227B is significantly associated with cardiovascular phenotypes, that PDE8B is enriched in endocrine/metabolic pathways, and that PDE10A has strong genetic links to neurological diseases." (PMID 41570039, 2026).
genetic diseases (1 paper, 2025). "Furthermore, mutations in several PDE genes, including PDE8B,7, 8, 9, 10PDE2A,11, 12 and PDE10A,13, 14, 15, 16, 17, 18 underlie rare genetic diseases manifested mainly by movement disorders." (PMID 40492975, 2025).
movement disorder (1 paper, 2021). Neurological conditions resulting in abnormal voluntary or involuntary movement, which may impact the speed, fluency, quality and ease of movement. "Two other PDE isoenzymes, PDE4B and PDE8B, have been implicated in the pathogenesis of movement disorders." (PMID 34155691, 2021).
PDE8B also shares sentences with these, for which no sentence is quoted: autosomal dominant striatal degeneration (3 papers); adrenal cortical tumors (2); cardiac hypertrophy (2); adrenal tumors (1); Adult onset (1); Airway obstruction (1); autoimmune disease (1); cardiovascular diseases (1); Chorea (1); emphysema (1); endocrine disorders (1); epilepsy (1); heart failure (1); metabolic disease (1); pancreatic cancer (1); prostate tumors (1); Tremor (1).